POSTN (periostin)
Diseases named in the same sentence as POSTN in open-access papers (continued):
Sharing a sentence is not in itself a finding about the gene and the disease.
tumor (continued). "For cancer, reports highlight a tumor-suppressive role of TGFBI, and complementary expression patterns of periostin and TGFBI in the developing heart were explicitly studied." (PMID 20109226, 2010). "The gene list they identified shares similarities to gene expressed in our whole tumour sample (ANTXR1, COL12A1, COL5A2, CTHRC1, POSTN)." (PMID 19401702, 2009). "Whole tumour and parenchymal samples demonstrated differential gene expression, with 289 genes significantly overexpressed in the whole tumour, many of which were consistent with stromal gene expression (e.g., COL6A3, COL1A2, POSTN, TIMP2)." (PMID 19401702, 2009). "Some proteins from this list have also been identified in tumor studies as clinical outcome predictors (NOV, CLU TNC, POSTN, IGFBP2, LCN2) or mediators of resistance to chemotherapy (CLU, FBLN1, THBS, STIP1, PTGES3, IGFBP4, ATOX1)." (PMID 19936259, 2009). "Although we did not observe clear differences in POSTN expression in benign versus malignant human samples, sample size and tumor heterogeneity were likely confounders (as suggested by frequent differences in expression scores in duplicate cores)." (PMID 39511408, 2025). "Notably, the combined inhibition of POSTN in SCLC and the NOTCH pathway in HSCs synergistically inhibited SCLC proliferation, resulting in a significant reduction in tumor growth." (PMID 39762921, 2025). "Surrounding tumour nests, we found distinct peritumoral stromal regions positive for POSTN/α-SMA (i.e., myoCAFs) that did not appear to express GSN, and sub-populations expressing TRPA1." (PMID 40640495, 2025). "Additionally, when silencing POSTN, TAM density was sensibly reduced, thus reinforcing the idea that GSCs can recruit TAMs and foster tumor growth by secreting POSTN." (PMID 39981232, 2025). "Specifically, the mechanism for how SCLC-derived POSTN affects tumor microenvironment has not been fully elucidated." (PMID 39762921, 2025). "Moreover, we identified five molecules (SCGB1B2P, SFRP2, POSTN, COL3A1, ENTPD6) that were universally overexpressed in medullary cells infiltrated by IBC tumours." (PMID 40624675, 2025). "Therefore, this study aimed to clarify the clinicopathologic significance of periostin and Smad2/3 expression in CRC, with a particular focus on the tumor microenvironment." (PMID 39941916, 2025). "Furthermore, activated CAFs release SDF-1/CXCL12, OPN, periostin, galectin, THBS2, MFGE8, and diverse cytokines such as IL-6 and IL-32, which promote the EMT, tumor invasion, and tumor metastasis." (PMID 40352270, 2025). "In this review, the structure and isoforms of POSTN will be summarized, and the relationship between POSTN-integrin signaling and the diagnosis and prognosis of HCC patients, tumor cell proliferation and metastasis, immune escape, cancer stem cells and angiogenesis will be reviewed." (PMID 41018265, 2025). "There was a significant negative correlation between POSTN+ CAFs infiltration and CD8+ T cell infiltration, while there was a significant positive correlation between POSTN+ CAFs and T cell exclusion, which is responsible for the exclusion of T cells from malignant regions in HCC tumor tissue." (PMID 41018265, 2025). "Furthermore, the results of the immunohistochemical tests were validated and corroborated by the expression of the POSTN and PDPN genes at the mRNA level, which was detected in 100% (n = 28) of the tumours analyzed using the Real-time PCR method." (PMID 41361308, 2025). "A group of genes, including collagen type I alpha 1 (COL1A1), fibronectin 1 (FN1), laminin subunit gamma 2 (LAMC2), periostin (POSTN), transforming growth factor beta induced (TGFBI), are involved in extracellular mesenchymal organization and affect tumor behavior, akin to our findings." (PMID 40303998, 2025).
tumor (continued). "Proteins such as periostin (POSTN), versican (VCAN), collagen type XI alpha 1 (COL11A1), and collagen triple helix repeat containing-1 (CTHRC1), through TGF-β signaling, participate in CAF activation and promote tumor progression." (PMID 40136652, 2025). "miR-876 and neurogenic locus notch homolog (Notch) signaling directly regulate POSTN transcription in HCC cell lines, which could affect ECM organization and facilitate the transformation and invasion of tumor cells." (PMID 41018265, 2025). "Moreover, in a validation cohort of 68 HNSCC samples, we confirmed the prevalence of POSTN+ fibroblasts and SPP1+ macrophages in the tumor stroma." (PMID 38519500, 2024). "In this study, the impact of using the established five tumour-based EMT markers consisting of E-cadherin (E-cad), β-catenin (β-cat), Snail, Zeb-1, and Fascin in combination with the stromal periostin (PN) on the prediction of CRC patients’ prognosis were invesigated." (PMID 38935747, 2024). "However, in the tumor only the expression of CTGF was increased, while periostin and FN were unchanged." (PMID 38279150, 2024). "Since studies have indicated that POSTN secreted by GSCs recruits M2 TAMs and promotes the malignant growth of GBM, we hypothesized that POSTN might also recruit microglia to the tumor microenvironment." (PMID 39227950, 2024). "The role of periostin (POSTN) in remodeling the microenvironment surrounding solid tumors and its effect on the tumor cells in non-small-cell lung carcinoma (NSCLC) have not yet been fully understood." (PMID 39272978, 2024). "In BC, POSTN-positive stromal cells were recently demonstrated to guide lymphovascular invasion by cancer cells, and DKK3 was demonstrated to orchestrate activation of YAP/TAZ, which is required to induce tumor-promoting phenotypes." (PMID 39335478, 2024). "In addition, the impact of POSTN on angiogenesis, especially through its regulation of the Erk/VEGF pathway, is a crucial element enabling the tumor to continue its growth and metastasis." (PMID 39272978, 2024). "Subsets of these genes (POSTN and DPYSL3) were additionally validated using immunohistochemistry in an independent cohort of follicular thyroid tumors showing a clear gradient pattern from the core to the periphery of the tumor." (PMID 38280140, 2024). "Furthermore, our above investigations have identified that proliferative tumor cells predominantly reside in close proximity to the triad structure, which comprises SPP1‐expressing macrophages, endothelial cells, and POSTN+FAP+ fibroblasts (middle)." (PMID 39716897, 2024). "As a component of the tumor microenvironment, periostin is one of the matricellular proteins, a group of non-structural matrix components that plays a critical role in tumorigenesis and metastasis." (PMID 38279150, 2024). "Furthermore, these phenomena were induced through the activation of the PI3K/AKT/mTOR pathway, and they were observed to enhance the expression of periostin (POSTN) and N-cadherin in the EMT around the tumour tissues." (PMID 39120301, 2024). "In addition to the interaction between POSTN+ fibroblasts and SPP1+ macrophages, we were interested in how they influence tumor cells because we found that their interaction weight with tumor cells increased from the NT to A stage." (PMID 38519500, 2024). "We proved that the pathological POSTN with exon 17 inhibition in stroma but not cancer significantly suppressed primary tumor growth and metastasis." (PMID 39272982, 2024). "In conclusion, our study has shown that POSTN could play a significant role in NSCLC, promoting angiogenesis and influencing tumor progression." (PMID 39272978, 2024). "Furthermore, the interaction between POSTN+ fibroblasts and SPP1+ macrophages contribute to ECM remodeling and coordinates to form a desmoplastic microenvironment by enhancing tumor cell ECM-receptor interactions, and cell-substrate junction organization." (PMID 38519500, 2024).
tumor (continued). "In addition, transfection of sh‐circ‐POSTN reduced circ‐POSTN expression and FYN protein level, but increased miR‐876‐5p expression in tumor tissues of the sh‐circ‐POSTN group and sh‐circ‐POSTN+IR group." (PMID 38553795, 2024). "To further investigate the effect of CAFs with or without POSTN on papillary thyroid tumor cell growth, we cultured tumor cells alone or co-cultured with WT CAFs or KO CAFs." (PMID 38773979, 2024). "Immunohistochemical staining of mouse xenograft tumors and clinical papillary thyroid tumors also revealed that POSTN was deposited in CAFs but not in tumor cells." (PMID 38773979, 2024). "Because the infiltration and interaction of POSTN+ fibroblasts and SPP1+ macrophages were greatest in the A stage, we then analyzed the ligand‒receptor (LR) interaction between these two cell types and tumor cells." (PMID 38519500, 2024). "Furthermore, the presence of SPP1+ macrophages in the triad structure, alongside endothelial and POSTN+ FAP+ CAFs, suggests a role in promoting tumor development through pro‐angiogenic properties and activation of CD44 in tumor cells." (PMID 39716897, 2024). "Periostin, however, appears to be the primary ECM that influences ALK-driven tumor biology." (PMID 38451815, 2024). "Using the Robust Cell Type Decomposition (RCTD) algorithm, we projected cell types based on gene expression matrices from scRNA‐seq data to the spatial transcriptomic map and found that POSTN+ CAFs and SPP1+ macrophages were enriched in another two tumours (P19 and P47, both stage III)." (PMID 38115703, 2023). "Periostin (POSTN), a soluble protein overexpressed and secreted by VHL non-expressing (VHL−) cells, promoted metastasis by enhancing the motility of VHL-WT cells and facilitating tumor cell vascular escape." (PMID 37069149, 2023). "Compared with cluster 2 tumor cells, cluster 1 tumor cells communicated with microglia more actively through the IL17 signaling pathway, the IFN-II signaling pathway, the VEGF signaling pathway, and the PERIOSTIN signaling pathway." (PMID 37122693, 2023). "Many members of this family, such as periostin, osteopontin (SPP1), or the CNN (Cyr61, CCN2, CCN3) family of proteins, have been shown to regulate key aspects of tumor biology, including proliferation, invasion, matrix remodeling, and dissemination to pre-metastatic niches in distant organs." (PMID 37240298, 2023). "While there were some IHC markers that are known to be more present in the stromal component (e.g. POSTN, COL11A1), our ovarian TMA was created to maximize the tumor epithelial tissue and the IHC scoring was based on the expression in the tumor epithelial compartment." (PMID 36761962, 2023). "POSTN is a 93 kDa nonstructural extracellular matrix protein that participates in various tumour biological processes, such as proliferation, invasion, matrix remodelling, and the formation of the cancer stem cell niche and premetastatic niche." (PMID 37199594, 2023). "In this study, we identified a POSTN isoform lacking exon 17 (Iso5) as a promoting factor of tumor progression via p‐EMT program in HNSCC." (PMID 36691359, 2023). "Towards this end, we examined tumor promotion in mice lacking Periostin following transverse aortic constriction (TAC)." (PMID 38139195, 2023). "Expression profiling of tumor tissues from treated mice revealed a unique gene signature induced by erlotinib+MLN0128, consisting of downregulation of immunosuppressive chemokines in the tumor microenvironment, including C-C motif chemokine ligand 2 (CCL2) and periostin." (PMID 36831214, 2023). "Periostin expression was mostly relegated to the stroma, with no tumor cells found expressing this protein." (PMID 36859337, 2023). "Furthermore, when disrupting POSTN in the in vivo model, it significantly reduced the recruitment of the TAMs, especially those of the M2 phenotype and inhibited GBM tumor growth." (PMID 37274252, 2023).
tumor (continued). "Here, myCAFs in cholangiocarcinoma have been shown to secrete matricellular proteins like Periostin, growth factors like hepatocyte growth factor, and therefore activate pathways like PI3K/Akt or Hedgehog (Hh)-GLI, which leads to tumor progression and therapy resistance." (PMID 37686288, 2023). "Although no Periostin is detected in the serum derived from these mice, tumor growth that was monitored over time showed higher tumor volume in the TAC-operated POSTN(−/−) group as compared to the non-operated control." (PMID 38139195, 2023). "Based on our results, we speculated that stromal POSTN accelerated the metastasis of CRC cells via a CAF-A-like ECM-remodeling capacity and activated the migration of both tumor and stromal cells." (PMID 36765564, 2023). "Periostin-positive tumor tissues have a higher blood vessel density than periostin-negative tumor tissues." (PMID 36224629, 2022). "Nevertheless, specific molecular mechanisms defining how POSTN remodels distinct tumor microenvironments have not been fully accounted for." (PMID 35163164, 2022). "We identified that ES2 tumor cells do not express POSTN and this is consistent with the lack of secreted POSTN from ES2 cells." (PMID 35884543, 2022). "Moreover, POSTN is involved in the proliferation, progression, migration and epithelial-mesenchymal transition (EMT) of tumor cells." (PMID 36077762, 2022). "CRC EVs had a variety of different effects on other CAF markers (e.g., PDGFRβ or periostin), suggesting that they may play a role in the formation of different (non‐myofibroblastic) CAF subtypes in tumour stroma." (PMID 35595718, 2022). "Furthermore, we found that TMAO upregulates POSTN and activates the ILK/AKT/mTOR pathway, which induces tumor proliferation and migration." (PMID 35676936, 2022). "In pancreatic ductal adenocarcinoma, POSTN interacts with α6β4 integrin in cancer cells leading to phosphorylation of FAK and AKT through activation of the PI3K pathway and promoting the invasiveness of tumour cells by increasing the motility of cells." (PMID 35260891, 2022). "In addition, periostin regulates critical metastatic processes, such as EMT, motility, tumor cell survival, angiogenesis, and tumor cell stemness." (PMID 36224629, 2022). "In the absence of POSTN, the immunosuppressive function of these cells is reduced, which affects tumor progression." (PMID 35832544, 2022). "A model conciliating these data with ours would be that aggressive tumor cells trigger rapid and localized PSC activation into POSTN‐positive CAFs, leading to POSTN expression upregulation, probably through TGFβ ligand secretion, and explaining why POSTN‐positive CAFs correlate with poor prognosis." (PMID 36102377, 2022). "In addition, when periostin-producing cells were transplanted as xenografts into immunocompromised SCID-Beige mice, they showed a phenotype of tumor growth and angiogenesis." (PMID 36224629, 2022). "Nevertheless, it seems that periostin-targeted therapy in CRC could potentially be the right direction, because periostin plays multiple roles in tumor development, and is crucial in metastasis." (PMID 35056404, 2022). "We found a significant negative correlation between periostin tumor concentration and microvessel density at the invasive front." (PMID 35056404, 2022). "To demonstrate the physical proximity between tumor cells expressing INHBA and ECM-remodeling CAFs, we co-stained nodular and infiltrative BCCs for INHBA and Activin A-exposure signature genes like FN1 and POSTN using RNA FISH." (PMID 35986012, 2022). "Genes associated with tumor proliferation such as DSG2 and SPRR3 and genes related to energy metabolism process decreased along the invasion trajectory of the tumor, while the function of tumor progression-related gene BGN and metastasis growth-related gene POSTN gradually increased." (PMID 35899203, 2022).
tumor (continued). "Furthermore, it has been found that periostin is an EMT regulator and induces the expression of MMP-9, MMP10, and MMP-13, leading to ECM destruction, which is important for local tumor spread and metastasis." (PMID 36224629, 2022). "Moreover, higher expression of POSTN and HTRA3 positively correlated with infiltration of neutrophils, which can promote tumor progression." (PMID 35676936, 2022). "CTHRC1 with POSTN and MMP13 could potentially affect ECM remodelling which in turn could aid in tumor cell migration and invasion." (PMID 36190948, 2022). "A proteomic analysis of colorectal normal and tumor ECM revealed that collagen IV, V and XIV, fibrilin, emilin, vitronectin, laminin and endomucin have increased expression in tumor ECM, and that periostin, versican, thrombospondin-2 and tenascin were exclusively present in tumor tissue." (PMID 35053521, 2022). "We also observed similar findings in an independent PDAC dataset (GSE28735), in which POSTN mRNA level was increased in tumor sample compared to adjacent non tumoral tissue (not shown)." (PMID 35883700, 2022). "Here, we report that PCa periostin is mainly expressed in the peritumoral stroma and not in tumor cells." (PMID 35887333, 2022). "Finally, we performed qPCR validation in clinical tissue samples and showed highly expressed POSTN, VISG4 in tumor samples, and highly expressed CXCL10, CXCL13, and MMP12 in normal samples." (PMID 36212488, 2022). "There is also evidence that POSTN may regulate the EMT via the ERK signaling pathway, whose activation promotes the migration, invasion, and metastasis of tumor cells." (PMID 35057799, 2022). "POSTN and OGN are crucial in modulating the microenvironment and tumor biology for HNSCC." (PMID 33530209, 2021). "Furthermore, immunostaining analysis of A549 xenograft tumors showed that periostin was highly expressed in DIPF around tumor cells and the Ki-67-positive rate of tumor cells with DIPF was significantly higher than that of tumor cells with NHLF." (PMID 34702952, 2021). "Nevertheless, it is considered that periostin secreted by non-tumor stroma in IPF-LC plays an important role in tumor progression, especially in LC development, because LC is known to often arise de novo from an IPF lung." (PMID 34702952, 2021). "Our results show a significantly higher mRNA expression of MMP1, MMP9, POSTN, GREM1, FMOD, and COL1A2 in tumor biopsies compared to normal tissue, but the significant difference between responder and non-responder groups was only found for the expression of FMOD mRNA." (PMID 34283070, 2021). "Second, we were not able to clarify how periostin secreted by fibroblasts is actually transported from activated fibroblasts in non-cancerous areas to NSCLC cells in the human tumor microenvironment." (PMID 34702952, 2021). "Periostin (PON), which is a non-collagenous extracellular matrix molecule, has been implicated in tumor invasiveness." (PMID 34563225, 2021). "Interestingly, we found POSTN and OGN were common in all classification, indicating their key role in the tumor microenvironment and tumor progression." (PMID 33530209, 2021). "POSTN binds to integrins through its Fatty Acid Synthase (FAS) domains and activates the Akt/PKB and the FAK-mediated signaling pathways, which together contribute to increased tumor invasion, migration, and metastasis." (PMID 33513753, 2021). "Here POSTN promotes extravasation of TAMs into the tumour stroma through integrin-dependent mechanisms, rather than as a result of changes in ECM architecture." (PMID 33187209, 2020). "Some of these genes, which interfere with tumor cell growth/differentiation/migration/invasion (such as MYC, MET, PROM1, and PTK2), induce hypoxia (such as ARNT2, HIF3A, TGB2, MMP2, and POSTN) and genes regulating transcription via acetylation were downregulated upon pembrolizumab treatment." (PMID 32616706, 2020).